IGF2BP1 (insulin like growth factor 2 mRNA binding protein 1)
Diseases named in the same sentence as IGF2BP1 in open-access papers (continued):
Sharing a sentence is not in itself a finding about the gene and the disease.
liver cancer (34 papers, 2017 to 2025). An epithelial or non-epithelial malignant neoplasm that arises from the liver. "IGF2BP1 was predominantly localized in the cytoplasm, and upregulation of IGF2BP1 expression was associated with tumor progression, including liver cancer." (PMID 40448098, 2025). "Other m6A methylation readers, such as YTHDF3 and IGF2BP1/2/3, are closely linked to immune therapy in liver cancer." (PMID 39911396, 2025). "Finally, the RBP IGF2BP1 (IGF2 mRNA-binding protein-1) destabilizes the liver-cancer-associated lncRNA HULC (Highly Upregulated in Liver Cancer) in a CNOT1-dependent manner." (PMID 39941720, 2025). "We inferred that other published miR-140 targets, such as ADAMTS5 and IGFBP5 in colorectal cancer, Pin1 in liver cancer, and IGF2BP1 in cervical cancer, which are associated with tumor migration and invasion, may contribute to these GC cell phenotypes." (PMID 28818100, 2017). "For instance, IGF2BP1 typically promotes tumor growth in breast and liver cancers, while IGF2BP2 and IGF2BP3 are involved in enhancing the proliferation and metastasis of certain cancers, such as colon cancer." (PMID 40088376, 2025). "Recent research has shown that PRMT3 methylates IGF2BP1 at R452, contributing to oxaliplatin resistance in liver cancer patients." (PMID 40050608, 2025). "Meanwhile, IGF2BP1 promotes the growth of tumor cells such as liver cancer by enhancing the expression of a variety of serum response factor (SRF) target genes, including PDLIM7, FOXK1, MKI67 and MYC." (PMID 38166832, 2024). "In tumors, TRIM71 stabilizes m6A-modified CEBPA mRNA dependent on IGF2BP1, and ultimately facilitates liver cancer progression." (PMID 39267787, 2024). "It has been reported that a research team used cucurbitacin B as a probe to directly target IGF2BP1 in liver cancer cells." (PMID 39275042, 2024). "Firstly, the IGF2BP1 mRNA level was increased in human liver cancer cell lines (Huh7, MHCC97H) comparing to normal human hepatic cells (THLE-3)." (PMID 39606242, 2024). "Since IGF2BP1 has most target records among m6A readers in HepG2, a liver cancer cell line, we selected IGF2BP1 as the potential m6A effector in liver cancer." (PMID 36300630, 2023). "For example, IGF2BP1 facilitated hthe stemness of liver cancer cells by enhancing mannoside acetylglucosaminyltransferase 5 (MGAT5) mRNA stability via m6A modification." (PMID 37370759, 2023). "On the other hand, IGF2BP1/2/3 stabilize specific m6A-modified mRNA, enabling fine-tuned regulation of immune-related gene expression, which in turn indirectly affects the overall outcome of liver cancer immunotherapy." (PMID 39911396, 2025). "IGF2BP1 arginine methylation mediated by protein arginine methyltransferase 3 (PRMT3) promotes oxaliplatin resistance through stabilizing the mRNA of HEG1 in liver cancer." (PMID 40592832, 2025). "Downstream target gene IGF2BP1 of let-7c-5p is proved to be widely expressed in embryos and tumor tissues, to play an important role in controlling embryonic development, and to serve as a carcinogen in most cancers including liver cancer, glioblastomas, and gastric cancer." (PMID 35368660, 2022). "In liver cancer, PRMT3 directly binds to IGF2BP1 and methylates its Arg501 residue, enhancing IGF2BP1’s stability toward target mRNAs and promoting oxaliplatin resistance." (PMID 41583428, 2025). "Mechanistically, TRIM71 formed a protein complex with IGF2BP1, bound to and stabilized the mRNA of CEBPA in an m6A-dependent manner, enhance the serine/glycine metabolic pathway, and ultimately promoted liver cancer progression." (PMID 39267787, 2024). "In our work, we performed IP-mass and co-IP assays and identified the protein complex formed by TRIM71 with IGF2BP1, which stabilized CEBPA mRNA levels through an m6A-dependent manner in liver cancers." (PMID 39267787, 2024). "As a m6A reader, IGF2BP1 stabilizes mRNA such as SRF to promote cell growth and invasion in ovarian and liver cancer." (PMID 35346372, 2022).
liver cancer (continued). "High expression of IGF2BP1 promoted proliferation, migration, and invasion of NSCLC cells and liver cancer cells." (PMID 33795529, 2021). "IGF2BP1 can also stabilize c-MYC and MKI67 mRNA and promote their expression, thereby regulating the proliferation and apoptosis of liver cancer cells." (PMID 32653017, 2020). "In the IGF2BPs family, IGF2BP1 can reduce the stability of HULC mRNA which is specifically and highly expressed in liver cancer." (PMID 32653017, 2020). "Meanwhile, IGF2BP1 could increase the stability of heart development protein with EGF-like domains 1 (HEG1) mRNA in an m6A-dependent way, which subsequently increases liver cancer cell resistance to oxaliplatin." (PMID 40584294, 2025). "TRIM71 forms a protein complex with IGF2BP1, enhances mRNA stability of CEBPA with m6A-dependent manner, remodels PSPH and PSAT1 transcription, strengthens serine/glycine metabolism, and ultimately promotes liver cancer progression." (PMID 39267787, 2024). "In addition, different readers can play opposite roles in the same cancer; IGF2BP1 is an important protumorigenic factor in pancreatic cancer, nevertheless, YTHDF2 is poor expressed in liver cancer and inhibits cancer cells proliferation and growth." (PMID 35915142, 2022). "Moreover, the depletion of IGF2BP1 had been shown to lead to an increased HULC half-life and expression, which is a long non-coding RNA highly up-regulated in liver cancer." (PMID 33575259, 2020). "Importantly, it forms a protein complex with IGF2BP1, which binds to and stabilizes CEBPA mRNA levels through an m6A-dependent manner, enhancing CEBPA mediated PSPH/PSAT1 transcription and remodeling serine/glycine metabolism, and ultimately accelerates liver cancer growth and tumorigenicity." (PMID 39267787, 2024).
colorectal cancer (29 papers, 2013 to 2025). A primary or metastatic malignant neoplasm that affects the colon or rectum. "The risk of colorectal cancer incidence significantly increases in carriers with the C allele in SNP rs6504593 located in IGF2BP1 (Insulin-Like Growth Factor-2 Binding Protein-1)." (PMID 35330456, 2022). "It was reported that 3′ UTR shortening of insulin-like growth factor mRNA binding protein 1 (IGF2BP1) led to the loss of let-7 regulation in colorectal cancer patients, resulted in elevated IGF2BP1 expression, and accelerated liver metastasis." (PMID 32276464, 2020). "Xie and colleagues indicated that miR-21 bound to SNP rs6504593 in IGF2BP1 could regulate the expression of IGF2BP1 and develop colorectal cancer risk." (PMID 35330456, 2022). "IGF2BP1 knockdown has been shown to reduce resistance to chemotherapeutic drugs (e.g. 5-fluorouracil, irinotecan, and oxaliplatin) in colorectal cancer (CRC) cells." (PMID 39731162, 2024). "IGF2BP1 has been shown to enhance β-TrCP1, expression in colorectal cancer, establishing its role in CRC progression." (PMID 37829185, 2023). "We used the HCT116 colorectal carcinoma cell line that has low levels of IGF2BP1, but high IGF2BP2 expression." (PMID 37582618, 2023). "The knockdown of c-Myc in colorectal cancer cell lines increases the expression of mature let-7 miRNA family members and downregulates IGF2BP1." (PMID 34203267, 2021). "In this study, we found that overexpression of IGF2BP1 in colorectal cancer cell lines, namely HCT116 and DLD-1, increased colony formation and increased drug resistance to 5-FU and etoposide." (PMID 34203267, 2021). "The mutation allele of rs6504593 reduced the binding of miR‐21 to the IGF2BP1 3ʹ‐UTR and increased IGF2BP1 expression, which leads to the initiation of colorectal cancer." (PMID 30569605, 2019). "This is consistent with the severe upregulation of IGF2BP1 in various malignancies and correlates well with IGF2BP1 de novo synthesis observed in colorectal carcinomas." (PMID 23069990, 2013). "The signature might provide five candidate targets (RBMX, FMR1, IGF2BP1, LRPPRC, YTHDC2) associated with specific clinical features, prognosis and improvement in immunotherapy for patients with colorectal cancer." (PMID 37194014, 2023). "Furthermore, the directed biological function of the combination of miR‐21 and IGF2BP1 in colorectal cancer should be conformed in the future to identify the functional relationship between miR‐21 and IGF2BP1." (PMID 30569605, 2019). "However, the clinicopathological roles of IGF2BP1 in colorectal cancer (CRC) remains limited." (PMID 34203267, 2021). "Furthermore, overexpression of IGF2BP1 is found to be associated with increased c-MYC and RAS expressions, while loss of IGF2BP1 could induce caspase-3 and PARP-mediated apoptosis in colorectal cancer cell lines." (PMID 28693523, 2017). "Likewise, we still have little information on a putative co-regulation of IGF2BP1 and target mRNA expression in primary tumor samples, although the expression of IGF2BP1 has, for instance, been correlated with lymph node metastasis of colorectal carcinomas." (PMID 23069990, 2013). "Previous studies have demonstrated that IGF2BP1 enhances WNT pathway signalling and that downregulation of IGF2BP1 can reduce the resistance of chemotherapy-resistant cancer cells that have an activated Wnt/β-catenin signalling pathway in colorectal carcinomas (CRC)." (PMID 40629079, 2025). "To clarify the role of RBMX, FMR1, IGF2BP1, LRPPRC and YTHDC2, we analyzed the mRNA expression patterns in human colorectal cancer specimens." (PMID 37194014, 2023). "As an example, we constructed Kaplan-Meier curves for IGF2BP1, or IMP-1, which we described previously as a modulator of tumor growth in colorectal cancer." (PMID 28787442, 2017).
colorectal cancer (continued). "Besides, we have revealed that LINC02418 plays a significant part in the activation of Wnt pathway and promoting colorectal cancer progression via binding to YBX1 and IGF2BP1 protein to perform transcriptional and post-transcriptional regulation of CTNNB1." (PMID 40082414, 2025). "We found that rs6504593 genotypes had no influence on IGF2BP1 expression in either colorectal cancer tissues or normal tissues (P = 0.705 and P = 0.774, respectively)." (PMID 30569605, 2019).
lung carcinoma (28 papers, 2018 to 2025). "Consistently, 35 SRF/IGF2BP1-dependent genes showing conserved association with SRF and IGF2BP1 expression indicate a poor overall survival probability in ovarian, liver and lung cancer." (PMID 30371874, 2019). "Pathway analysis reveals that AVJ16 treatment leads to a downregulation of the WNT pathway, implicated in lung cancer tumorigenesis, and the genes affected are, in most cases, IGF2BP1-regulated genes, as validated by the shRNA knockdown of IGF2BP1 and confirmed by co-expression analysis." (PMID 40629079, 2025). "Recently, a seven-gene m6A/m5C risk model, comprising METTL3, NPLOC4, RBM15, YTHDF1, IGF2BP1, NSUN3, and NSUN7, was developed to stratify the prognosis of early-stage lung cancer." (PMID 40279954, 2025). "The positive feedback loop involving c‐Myc/MNX1‐AS1/IGF2BP1 accelerates cell cycle progression and fosters sustained proliferation of lung cancer cells." (PMID 40211955, 2025). "Mechanistically, circCRIM1 bound to the IGF2BP1 protein and then destabilized the HLA-F mRNA, ultimately contributing to the attenuation of lung cancer immune evasion." (PMID 36672208, 2023). "Recently, the necroptosis-related gene IGF2BP1 was reported to play crucial roles in the progression and prognosis of lung cancer." (PMID 37968457, 2023). "In lung cancer, circXPO1 has also been reported to promote tumor progression by interacting with IGF2BP1." (PMID 36980172, 2023). "KrasG12V is known to be a driver mutation for lung adenocarcinomas, and we have shown that Igf2bp1 not only binds Kras RNA in mouse lung carcinoma (LKR-M) cells but also synergizes with mutant Kras in promoting human lung adenocarcinomas." (PMID 34895045, 2022). "The mA regulator signatures KIAA1429, METL3, and IGF2BP1 have been identified as independent prognostic models that can stratify patients, evaluate prognosis, and personalize treatment for lung cancer." (PMID 36061307, 2022). "LINC01426 contributes to clear cell renal cell carcinoma progression by modulating CTBP1/miR-423-5p/FOXM1 axis via interacting with IGF2BP1, and to lung cancer progression via AZGP1 and predicts poor prognosis in patients with LUAD." (PMID 35818395, 2022). "Opposite to miR490, IGF2BP1 expression is up-regulated, and the high expression level of IGF2BP1 showed poor overall survival outcomes in lung cancer." (PMID 32426332, 2020). "Previous study has reported that the expression IGF2BP3 or IGF2BP1 can predict poor overall survival in lung cancer patients, which were consistent with our results." (PMID 32071816, 2020). "Previous studies have reported that the expression IGF2BP1, TLR8, PIWIL4, and GAPDH were associated with tumorigenesis and progression of lung cancer patients, which consistent with our results." (PMID 32087603, 2020). "Their expression is associated with an overall poor survival probability in ovarian, liver and lung cancer supporting the notion that SRF/IGF2BP1-enhanced gene expression is a conserved driver of oncogenesis that promotes both tumor growth and metastasis." (PMID 30371874, 2019). "In agreement, IGF2BP1 expression showed the most significant and conserved association with elevated SRF expression in ovarian, skin, liver and lung cancer, as determined by Pearson correlation of RNA-sequencing data available via the TCGA." (PMID 30371874, 2019). "At present, at least two miRNAs have been identified to inhibit lung cancer development partly by targeting 3′-UTR of IGF2BP1." (PMID 29954406, 2018). "The human lung cancer cell line H1299 expresses high levels of IGF2BP1." (PMID 40629079, 2025). "The analysis indicates that many RNAs downregulated by AVJ16 treatment are significantly enriched in gene sets associated with transformed phenotypes and signaling pathways activated during cancer progression, in accordance with known roles of IGF2BP1 in lung carcinoma." (PMID 40629079, 2025).
lung carcinoma (continued). "The current investigation revealed that tRF‐16 promotes the proliferation of lung cancer cells through its interaction with IGF2BP1, indicating that IGF2BP1 could serve as a significant target for cancer treatment." (PMID 39679845, 2024). "In addition, compared with adjacent cancer tissues and normal lung epithelial cells, we observed increased IGF2BP1 mRNA expression in lung cancer tissues and cells." (PMID 39679845, 2024). "Although we focused on the role of HEG1 as an effector for IGF2BP1 function in OXA resistance, BTBD7 may be also involved in OXA resistance as it has been implicated in chemoresistance in lung Carcinoma A549 Cells54." (PMID 37024475, 2023). "For example, IGF2BP1 expression implies a poor prognosis in ovarian, liver and lung cancers." (PMID 33926554, 2021). "This means that the tumor-suppressive role of miR-494 by downregulating IGF2BP1 in lung cancer might be covered by other carcinogenic effects from elevating IGF2BP1 levels." (PMID 29954406, 2018). "Thus, IGF2BP1 detection could potentially lead to false-positive diagnosis in the case of a rarely observed lung cancer-derived metastasis to the thyroid." (PMID 32719445, 2021). "We have explored the mechanism of action of the IGF2BP1 inhibitor AVJ16 and examined its effects on lung carcinoma cells in 2D and 3D culture systems, and in mice." (PMID 40629079, 2025). "This study showed that tRF‐16 can decrease IGF2BP1's ability to bind to CPT1A and decrease CPT1A's stability, which can impact lung cancer cells' fatty acid metabolism and promote both in vivo and in vitro growth." (PMID 39679845, 2024). "Furthermore, IGF2BP1 directly interacted with tRF‐16, and later cellular tests indicated that tRF‐16 may impede lung cancer cell growth via modulating IGF2BP1 to suppress fatty acid metabolism in lung cancer cells." (PMID 39679845, 2024). "To evaluate the expression profile of m6A readers in lung cancer, we analyzed known readers, including YTHDF1/2/3, YTHDC1/2, HNRNPA2B1, HNRNPC/G, eIF3A, FMR1 and IGF2BP1/2, in LUAD and lung squamous cell carcinoma (LUSC) via the GEPIA database." (PMID 33232910, 2021). "To further determine the expression of these hub RBPs in LUAD, we used immunohistochemistry results from the Human Protein Atlas database to show that IGF2BP1, PABPC1, and GAPDH were significantly increased in lung cancer compared with normal lung tissue." (PMID 32087603, 2020). "Besides, IGF2BP1-phase separation is associated with c-myc-mediated progression and proliferation in lung cancer cells mediated by MNX1-AS1, implying the MNX1-AS1/IGF2BP1 axis may serve as a potential biomarker and therapeutic target in NSCLC20." (PMID 37968457, 2023). "To assess the specificity of this effect, we made use of a mouse lung carcinoma line, LKR-M, that has been selected to be highly metastatic but does not express endogenous IGF2BP1." (PMID 40629079, 2025). "To validate the involvement of YTHDF3 and IGF2BP1 in the regulation of JUN and JUNB expression, we confirmed the knockdown effects in protein and mRNA expression in A549 and LC2/ad lung cancer cells with or without TGF-β treatment." (PMID 36183833, 2022). "Previously, studies have investigated the role of thirteen m6A regulatory genes in lung cancer, but the roles of seven newly discovered ones, namely, METTL16, YTHDF3, IGF2BP1, IGF2BP2, IGF2BP3, HNRNPG, and HNRNPA2B1 has not been determined." (PMID 33795529, 2021).